MST1 (macrophage stimulating 1)
Diseases named in the same sentence as MST1 in open-access papers (continued):
Sharing a sentence is not in itself a finding about the gene and the disease.
hepatocellular carcinoma (37 papers, 2011 to 2025). A malignant tumor that arises from hepatocytes. "Loss or inactivation of MST1 has been found in many tumors, including colorectal cancer, hepatocellular carcinoma, and soft-tissue sarcoma." (PMID 29367697, 2018). "In addition, Mst1 is associated with the survival, development and metastasis of colorectal cancer, non-small cell lung cancer and hepatocellular carcinoma." (PMID 29760744, 2018). "Similarly, mouse Mst1/2 deficiency in the liver results in the loss of inhibition of Yap1, massive liver overgrowth and hepatocellular carcinoma formation." (PMID 24489653, 2014). "Zhou and colleagues established that combined Mst1/Mst2 deficiency in the liver results in massive overgrowth and hepatocellular carcinoma as the loss of Mst1/Mst2 signaling abrogates Yap1 phosphorylation, leading to enhanced Yap1 activity in the nucleus and an increased transcriptional activity." (PMID 22363786, 2012). "In another study, loss of Mst1/2 or conditional overexpression of YAP in response to bile acid induced injury in liver cells was shown to cause Hepatocellular carcinoma (HCC) in mice models." (PMID 31231648, 2019). "To establish the pathological relevance of SPTAN1, NUMB, MARK, WW45, and Hippo/MST1/2/YAP signals in patients with hepatocellular carcinoma (HCC), we examined 60 pairs of liver-derived tumorous and adjacent nontumorous tissues." (PMID 37843276, 2023). "Our results revealed that α-hederin acted as a new agonist of the Mst1-mediated Hippo signaling pathway and played an inhibitory role in hepatocellular carcinoma (HCC) growth through inhibiting YAP activity." (PMID 35311132, 2022). "Sphingosine-1-phosphate activates YAP in an MST1/2-independent manner in human hepatocellular carcinoma cells." (PMID 34773076, 2021). "Intriguingly, MST1 disrupted the secretion of TLR4/9-triggered inflammatory cytokines to avoid chronic inflammation in hepatocellular carcinomas (HCCs) via priming the degradation of IRAK1 in macrophages." (PMID 32849504, 2020). "In hepatocellular carcinoma, Notch signaling cannot only be activated by YAP, but also maintains a positive feedback loop in Mst1/2-deficient livers to enhance YAP signaling and tumorigenesis." (PMID 30931304, 2019). "High quality SPECT images with zero background were successfully obtained in a subcutaneous 4T1 tumor model and deep tumors in critical locations, such as an orthotopic LM3 tumor model and Mst1/2 double-knockout hepatoma model." (PMID 29780557, 2018). "Single photon emission computed tomography (SPECT) images with zero background were successfully achieved in a subcutaneous 4T1 tumor model, an orthotopic LM3 tumor model, and even in a Mst1/2 double-knockout hepatoma model." (PMID 29780557, 2018). "Combined loss of Mst1/2 (homologues of Drosophila Hippo) resulted in loss of YAP phosphorylation, leading to a massive overgrowth and hepatocellular carcinoma." (PMID 26821647, 2016). "In fact, transgenic overexpression of YAP and liver-specific knockout of Mst1/2 or Sav1 induce abnormal liver expansion in terms of size, and eventually hepatocellular carcinoma formation (HCC)." (PMID 22830020, 2012). "Moreover, other signaling molecules such as APC in the Wnt/ β‐catenin signaling pathway have been shown to negatively affect YAP in colon cancer, while MST1/2 deletion in the Hippo/YAP pathway was shown to activate β‐catenin in hepatocellular carcinoma." (PMID 37558205, 2023). "Thus, our data provided a novel mechanism of α-hederin in inhibiting hepatocellular carcinoma through the Mst1/2-mediated activation of Hippo signaling pathway." (PMID 35311132, 2022). "Moreover, Sirt1 regulates Mst1/YAP2 activation in hepatocellular carcinoma cells, thereby modulating tumor growth and progression." (PMID 32692720, 2020). "First, liver specific deletion of MST1/2 in mice causes hepatocellular carcinoma (HCC) by YAP deregulation without any apparent involvement of LATS1/2." (PMID 23985307, 2013).
hepatocellular carcinoma (continued). "We first examined IHMT-MST1-39 and XMU-MP-1 on AMPK activation in human hepatoma cells, and found that both MST1 inhibitors were able to activate AMPK at a similar concentration." (PMID 37015918, 2023). "About 30% of hepatocellular cancer cases show an inactivation of the tumor-suppressing proteins Mst1 and Mst2, and consequently, a high YAP/TAZ activity, indicating the contribution of Hippo in hepatocellular cancer." (PMID 34577571, 2021). "ROS levels can reportedly regulate the expression of MST1, which acts upstream of the Hippo pathway, as well as upregulate YAP mRNA and protein levels through the c-Myc pathway in hepatocellular carcinoma cells." (PMID 34650666, 2021). "Silencing of the Hippo upstream kinases Mst1 and Mst2 could activate the activity of YAP/TAZ and Wnt/β-catenin signaling, resulting in rapid hepatocellular carcinoma formation." (PMID 36620008, 2022). "It has recently been shown that Mst1/2 ablation leads to hepatocellular carcinomas and the inhibition of YAP2 by MST kinases are an important mechanism in tumor suppression, especially in the progression of HCC (hepatocellular cancer)." (PMID 21909427, 2011). "Inhibition of SIRT7 reversed MST1 levels and inhibited hepatocellular carcinoma (HCC) growth, demonstrating the SIRT7–MST1–YAP axis as a target." (PMID 41425553, 2025). "Several reports have shown that PDK1 can form complex with the Hippo components including MST1/2, SAV1, LATS1/2, and PDK1 recruited to the plasma membrane triggered by PI3K leads to dissociation of these complex and YAP activation in MCF-10A, HEK293T, and hepatocellular carcinoma cells." (PMID 34725466, 2021). "Mouse livers missing Mst1 and Mst2, or SAV1, have elevated YAP activity leading to hepatomegaly and hepatocellular carcinoma (HCC)." (PMID 25097728, 2014).
diabetes (28 papers, 2016 to 2026). "Mammalian Sterile 20-like kinase 1 (MST1) is a key mediator of β-cell failure and the identification of neratinib as MST1 inhibitor with potent effects on β-cell survival represents a promising approach for causative diabetes therapy." (PMID 35370966, 2022). "In summary, genetically induced MST1 deficiency normalizes glycemia, restores the function of β cells, and prevents the development of diabetes." (PMID 35054822, 2022). "The loss of kinase (MST1-knockout (MST1-KO) mice) prevents the progression of diabetes and restores normal cell function." (PMID 35054822, 2022). "Our results not only proved that asialo-rhuEPOP is cytoprotective toward beta-cells but also revealed that it can also suppress activation of MST1, a key player that determines the susceptibility of beta-cells to apoptosis and ultimately leading to diabetes." (PMID 28469576, 2017). "Other studies have implicated the related ste-20-like kinase MST-1 as a positive regulator of β cell apoptosis in diabetes, and loss of MST-1 promoted normoglycemia in diabetic animal models." (PMID 27226575, 2016). "The MST1 gene located in 3p21.31 is involved in the regulation of T cell selection, and its deficiency restores normoglycemia, improves beta cell function and prevents the development of diabetes." (PMID 36979105, 2023). "This conclusion is based on the results of genetic MST1 deficiency, which brought beneficial effects in the form of glycemic normalization and an improvement in β-cell function, survival, and the inhibition of diabetes development." (PMID 35054822, 2022). "Subsequently, Mst1 has been implicated in pathology related to cerebral ischemia-reperfusion injury, septic cardiomyopathy, atherosclerosis, neuroinflammation, and diabetes-related microvascular dysfunction." (PMID 32692720, 2020). "Importantly, MST1 would not only regulate the activation of apoptosis but it is also necessary for the desensitization of β-cells to glucose, the other hallmark of diabetes." (PMID 27322327, 2016). "The pro-apoptotic kinase Mammalian Sterile 20-like kinase 1 (MST1), an integral component of the Hippo pathway, is a key regulator of organ size, stress response, and tissue homeostasis; its aberrant hyperactivation is linked to multiple pathological disorders including diabetes." (PMID 35136036, 2022). "Under diabetogenic conditions, significant overexpression and autophosphorylation of MST1 in response to various chronic diabetes stimuli have been demonstrated in vitro and in vivo." (PMID 40468401, 2025). "In diabetes milieu, MST1 is activated to promote β-cell death via the mitochondrial apoptosis pathway." (PMID 40707469, 2025). "A review reported that pre-diabetes and diabetes stimulated MST1, resulting in its significant autophosphorylation, activation of programmed cell death, and apoptosis." (PMID 40468401, 2025). "MST1 deletion has been proved to improve β-cell survival and insulin secretion in models of diabetes induced by streptozotocin (STZ) or HFD, and a combination of HFD and streptozotocin (HFS/STZ)." (PMID 40707469, 2025). "MST1 is expressed in pancreatic beta cells and plays a role to the pathophysiology of diabetes mellitus." (PMID 39595079, 2024). "The importance of MST1 as a therapeutic target for diabetes has been demonstrated at the β-cell level and in diabetic complications." (PMID 37189611, 2023). "Mammalian sterile 20-like kinase 1 (MST1) contributes to the progression of diabetes mellitus through apoptosis induction and acceleration of pancreatic β cell dysfunction." (PMID 37015918, 2023). "In mice with experimentally induced diabetes, physical exercise was found to suppress MST1 expression and ameliorate cardiac remodeling." (PMID 38049831, 2023).
diabetes (continued). "In recent years, in vitro and in vivo studies on various research materials, including pancreatic islets obtained from animals and patients with type 2 diabetes, have shown that pre-diabetes conditions and those that reflect full-blown diabetes activate MST1." (PMID 35054822, 2022). "Studies of human β cells/pancreatic islets under experimentally induced diabetes have shown that the inhibitory effects of MST1 and LATS2, the major kinases of the Hippo pathway, exhibit high functional and anti-apoptotic efficacy." (PMID 35054822, 2022). "IHC revealed an increase in MST1 protein level in the heart tissues of diabetes-exposed embryos, that was confirmed by western blotting." (PMID 33568044, 2021). "Wildtype and Mst1 transgenic mice were challenged with streptozotocin (STZ) to induce experimental diabetes and were divided into sedentary and exercise groups." (PMID 33953853, 2021). "Here, we observed increased MST1 protein levels in the fetal heart tissue of rats exposed to diabetes." (PMID 33568044, 2021). "Active MST1 promotes pancreatic β cell apoptosis, a molecular process that resembles the progression of type-1 diabetes mellitus." (PMID 32987643, 2020). "The main finding of this study was that treatment with the MST1/2 inhibitor XMU-MP-1 produced a beneficial effect in improving glucose tolerance in the STZ-induced diabetic mouse model." (PMID 32987643, 2020). "Wild-type, Mst1 transgenic and Mst1 knockout mice were induced with experimental diabetes by streptozotocin injection." (PMID 33553168, 2020). "Equally important, studies using different models of diabetes, e.g., the high-fat-diet-induced diabetes model, also need to be conducted to understand if MST1/2 inhibition is also effective in controlling this type of pathological condition." (PMID 32987643, 2020). "We will be keen on evaluating the second-generation MST1 inhibitors derived from neratinib in diabetes, heart failure, liver regeneration, and IBD." (PMID 31815004, 2019). "The identification of MST1 inhibitors represents a promising approach for a β-cell-protective diabetes therapy." (PMID 31676778, 2019). "The identification and elaboration of MST1 inhibitors represents a promising approach to β-cell-protective drugs for the treatment of diabetes." (PMID 31676778, 2019). "The subject of our ongoing work in this regard is the design of neratinib-based MST1 inhibitors that exhibit enhanced potency and selectivity for MST1, with safety profiles commensurate with the chronic treatment of diabetes." (PMID 31676778, 2019). "MST1 was found to be a key mediator of apoptotic signaling in beta-cells and has been suggested as a novel target for the discovery of new drugs for diabetes." (PMID 28469576, 2017). "These, and experiments in animal models, indicate that this role of MST1 is central in the death of β-cells that is characteristic of both types of diabetes." (PMID 27322327, 2016). "Mst1 knockout significantly alleviated diabetes-induced cardiac dysfunction and microvascular injury without affecting non-diabetic hearts." (PMID 27680548, 2016). "Altogether, the over-expression of MST1 and the deficiency of TAZ and Tead1 may interfere with the transcription of PDX1, which further leads to the dysfunction of β-cells and diabetes." (PMID 40707469, 2025). "Consistent with previous studies, in which treatment with MST1/2 inhibitor XMU-MP-1 improves glucose tolerance in MLD-STZ induced diabetic model, we also observed significant improvement in intra-peritoneal glucose tolerance test in mice treated with IHMT-MST1-39 alone." (PMID 37015918, 2023). "Based on our results above, IHMT-MST1-39 would be not only a good pharmacological tool to investigate the MST1-mediated physiology and pathology, but also a potential drug candidate for the treatment of diabetes." (PMID 37015918, 2023).
diabetes (continued). "In conclusion, LATS2 may be a second therapeutic target alongside MST1, whose blockage of action may lead to improved function and increase β cell survival in diabetes." (PMID 35054822, 2022). "MST1 is a promising target for such strategy against diabetes." (PMID 35136036, 2022). "The effect of the strong MST1 inhibitor neratinib (the most widely controlled), documented in basic studies, is the basis for further research aimed at implementing a new diabetes treatment formula based on the maintenance of β-cell survival and function and the elimination of hyperglycemia." (PMID 35054822, 2022). "Diabetes was induced in C57BL/6 or Tg-Mst1 mice via an intraperitoneal injection of STZ." (PMID 33953853, 2021). "Overall, this study showed that MST1 could become a promising therapeutic target for diabetes mellitus." (PMID 32987643, 2020). "Our data support the idea that the key components of the Hippo signaling pathway, in this case MST1/2, could become a target for diabetes therapy." (PMID 32987643, 2020). "Through in-depth studies of key elements of the apoptotic machinery, we have previously found serine/threonine kinase mammalian sterile 20-like kinase 1 (MST1), a core kinase of the Hippo developmental pathway, as a critical regulator of β-cell death and dysfunction in diabetes." (PMID 31815004, 2019). "While neratinib is not at all selective for MST1, we believe that the underlying mechanisms of diabetes protection still derive from a direct protective effect on the β-cell mediated by MST1 and not from an effect on insulin sensitivity mediated by EGFR." (PMID 31676778, 2019). "Hence, MST1 has been suggested as a target for the discovery of new drugs for diabetes because of its critical role in beta-cell apoptosis and dysfunction." (PMID 28469576, 2017). "This prompted the investigation to determine whether Mst1 contributed to CMECs dysfunction in diabetes." (PMID 27680548, 2016). "Mst1−/− mice are also protected from diabetogenic stimulation, suggesting MST1 could be a potential therapeutic target for treating diabetes." (PMID 27805903, 2016). "Additionally, IHMT-MST1-39, a MST1 inhibitor, has demonstrated significant anti-apoptotic effects, effectively enhancing the survival of pancreatic β-cells under diabetes-inducing conditions and improving the viability of primary islets in ex vivo disease models." (PMID 40707469, 2025). "This clinical case reports the combination of HER2/EGFR/MST1-inhibition by neratinib for the pharmacological intervention to effectively restore normoglycemia in a patient with poorly controlled T2D and suggests neratinib as potent therapeutic regimen for the cancer-diabetes comorbidity." (PMID 35370966, 2022). "In individuals with diabetes, SIRT3 upregulates mitochondrial autophagy in the heart solely by inhibiting macrophage stimulating 1 (Mst1), and inhibiting SIRT3 expression impairs mitochondrial autophagy in myocardial cells, thereby exacerbating type 1 DCM." (PMID 37754811, 2023). "The encouraging anti-diabetic effects of combination therapy in vivo also suggested that simultaneous pharmacological inhibition of MST1 and activation of AMPK represents a novel promising approach for diabetes therapy." (PMID 37015918, 2023). "A study using another inhibitor of MST1, Neratinib—which also showed MST1 inhibition to be protective—was also performed using STZ-induced diabetes mellitus." (PMID 32987643, 2020). "Mst1 overexpression inhibited, while Mst1 knockout enhanced LVEF and LVFS in mice underwent diabetes insult." (PMID 33553168, 2020). "In keeping with this finding, genetic inhibition of MST1 protected against β cell apoptosis and improved the diabetic phenotype in streptozotocin (STZ)-induced diabetes model in mice." (PMID 32987643, 2020). "It implies that maintaining the expression of YAP/TAZ, which can be implemented by YAP/TAZ/TEAD1 activators or inhibitors of upstream kinases (MST1/2, LATS1/2), maybe a potential target in future diabetes treatment." (PMID 40707469, 2025).
diabetes (continued). "In this study, we investigated whether treatment with the MST1 inhibitor, XMU-MP1, would improve spermatogenesis and the sperm phenotype in a mouse model of diabetes mellitus." (PMID 39595079, 2024). "Thus, pharmacological inhibition of MST1 and activation of AMPK simultaneously represents a promising approach for diabetes therapy." (PMID 37015918, 2023). "Furthermore, a study using a cancer drug, neratinib, which was found to inhibit MST1 activity, indicated that pharmacological inhibition of MST1 was protective against the development of STZ-induced diabetes mellitus." (PMID 32987643, 2020). "The role of the pathway in neurodegenerative disease may have a close link to the possible involvement of MST1, LATS1 and other proteins of the pathway in the death of pancreatic β-cells that occurs in the development of diabetes." (PMID 27322327, 2016). "Diabetes led to impaired cardiac systolic function as manifested by decreases in left ventricular ejection fraction (LVEF) and left ventricular fraction shortening (LVFS), the effects of which were significantly alleviated by Mst1 knockout." (PMID 27680548, 2016). "Regarding the four prioritized proteins, individuals on BP medications had significantly lower circulating levels of FURIN and MST1, compared to individuals with hypertension but not on BP medication, even after excluding individuals with diabetes or lipid-lowering medications." (PMID 41065563, 2026). "Finally, the Mendelian randomization phenome-wide association study corroborated MANSC4 as a reliable target capable of mitigating the risk of various forms of diabetes, and it revealed the absence of adverse effects linked to CTRB1, SIGLEC5 and MST1." (PMID 38931433, 2024). "Unfortunately, it should also be remembered that theoretically, the inhibition of MST1 will not stop the Hippo pathway, and cell stress factors (those that lead to diabetes) may activate the second kinase of the LATS2 pathway (e.g., via Merlin)." (PMID 35054822, 2022).